EGFR (epidermal growth factor receptor)
Diseases named in the same sentence as EGFR in open-access papers (continued):
Sharing a sentence is not in itself a finding about the gene and the disease.
tumor (continued). "It should be noted that copy gains of EGFR, FGFR1, MET, and ERBB2 have already been reported to be predictive markers for certain tumor types." (PMID 31480645, 2019). "Overexpressed EGFR and overactivated EMT in TNBC can enhance tumorigenesis and tumor recurrence and metastasis, and metastasis is currently a limitation of TNBC treatment." (PMID 31214503, 2019). "As previously reported, the average IHC staining score for EGFR and PDGFR increased with tumor aggressiveness." (PMID 30642298, 2019). "Treatment with erlotinib (EGFR inhibitor) and a glutaminase inhibitor (CB-839) generates a metabolic crisis in EGFR mutant NSCLC cells, resulting in cell death and in rapid tumour regression in mouse NSCLC xenografts." (PMID 31795465, 2019). "Knockdown of EGFR, AREG or TGFα expression resulted in decreased tumor cell motility, slower growing tumor cells, and increased survival." (PMID 31681327, 2019). "In three cases where tumour tissue sequencing failed, amplifications in ERBB2, FGFR2, EGFR, and CCND1 were identified in ctDNA." (PMID 31137920, 2019). "ZR30 prevents MMP2 activation, thus limiting tumor invasion, blocking EGFR/Notch/AKT signaling, exerting an anti-tumor effect on different Glioblastoma cell subpopulations in a mouse model miming intratumor heterogeneity." (PMID 30832246, 2019). "Alteration of m6A levels participates in cancer pathogenesis and development via regulating expression of tumor-related genes like BRD4, MYC, SOCS2 and EGFR." (PMID 31801551, 2019). "Gainor and colleagues detected the level of PD-L1 in paired tumor tissues before EGFR-TKI treatment and tissues after development of resistance to EGFR-TKIs, and the results showed marked increases in PD-L1 expression in 12 patients (21%)." (PMID 31526368, 2019). "Gains of oncogenes including EGFR (7p12), ERBB2 (17q12), KRAS in the EGFR pathway were characteristic for LUAD and contribute to cell proliferation and tumor development, suggesting this is a core requirement for LUAD pathogenesis." (PMID 31448219, 2019). "Studies have shown that the EGFR/MAPK pathway is involved in cell proliferation, promote tumor development and play a key role in the development of CRC54-56." (PMID 31853225, 2019). "ENb-TRAIL simultaneously binds to EGFR and DR5 receptor, present on tumor cells, leading to receptor clustering and the induction of apoptotic signals, which resulted in a significant increase in survival 44,153." (PMID 31695800, 2019). "As proof of concept, we established a model of ectopic expression of two model proteins, carbonic anhydrase IX (CA IX) and epidermal growth factor receptor (EGFR), in the tumour cell line SKOV3." (PMID 30755643, 2019). "Anti-EGFR nanobodies anchored on extracellular vesicles via glycosyl phosphatidylinositol may improve the targeting ability of extracellular vesicles, highlighting the potential applications of these extracellular vesicles as a drug delivery system and new tool in EGFR-expressing tumor cells." (PMID 31620359, 2019). "Production of AREG is triggered by DNA damage to stromal cells, which passively enter senescence in the tumor microenvironment (TME), a process that remarkably enhances cancer malignancy including acquired resistance mediated by EGFR." (PMID 31493351, 2019). "Here we have used a cohort of well-characterized CRC organoids to study the influence of tumor heterogeneity on the activity of the KRAS/MAPK-signaling pathway and the consequences of treatment by inhibitors targeting EGFR and downstream effectors." (PMID 30925167, 2019). "Western blot and immunohistochemistry analyses demonstrated significantly reduced levels of phosphorylated EGFR and AKT in the primary tumor and metastatic tissues upon treatment with GZ17-6.02." (PMID 30899425, 2019). "The killing process of IgA-opsonized cells was also visualized for EGFR- and CD20-expressing target cells and demonstrated similar dynamics between neutrophils and tumor cells." (PMID 31031746, 2019).
tumor (continued). "This theranostic drug delivery system enabled drug accumulation in EGFR+ tumors, which was most pronounced using NGCA, and delayed tumor growth with little toxicity when compared to classical treatment with cisplatin." (PMID 31695800, 2019). "This suggests that dual inhibition of EGFR and IKK through Gefitinib and CmpdA synergy more effectively suppressed tumour growth in mice." (PMID 30585254, 2019). "Previous studies showed that both D281G and R248W mutants transactivate expression of tumor progression-related genes such as MYC, PCNA, EGFR, and EGR1; the D281G mutant shows an even greater transactivating activity than R248W in these studies." (PMID 30862120, 2019). "Our studies revealed that EGFR and HER2 are highly expressed in the primary tumours and metastases of CRC patients with ovarian metastases." (PMID 30858756, 2019). "Furthermore, EGFR was identified to be directly targeted by miR-27a, which restrained the activation of NF-κB via directly targeting EGFR, which indicates that miR-27a may act as a tumor suppressor through NF-κB pathway." (PMID 32039029, 2019). "A strong correlation was also found between tumor uptake of [64Cu]Cu-DOTA-cetuximab and adjusted EGFR band density (r = 0.915, p < 0.005)." (PMID 31651282, 2019). "On account of the high degree of tumour heterogeneity and adaptive cellular signalling pathways in NSCLC, the acquired osimertinib resistance is highly heterogeneous, encompassing EGFR-dependent as well as EGFR-independent mechanisms." (PMID 31564718, 2019). "When all of the mice were sacrificed, the tumor specimens were isolated and examined using immunohistochemistry, and the data suggested that the expression levels of CIP2A and EGFR were downregulated in the CuB-treated groups." (PMID 30759826, 2019). "The EGFR, PI3K/AKT, PTEN and mTORC signaling pathways play critical roles in tumor progression and drug resistance." (PMID 30940145, 2019). "To further ascertain the role of EGF/EGFR signaling in OC peritoneal dissemination, we used CRISPR/Cas9 editing to knock down EGFR in OC tumor cells." (PMID 30710055, 2019). "In line with an important role of EGFR and IL6 signaling in GLI-driven cancers, genetic and pharmacological inhibition of EGFR and IL6/JAK2/STAT3 signaling, respectively, interferes with GLI-driven tumor growth." (PMID 30991683, 2019). "Activation of the EGFR signal transduction pathway by EGF is known to play a role in cellular motility and size increase in the tumor aggressiveness." (PMID 31250984, 2019). "There are previous studies where regarding EGFR mutations we concluded that “tissue” is the issue, meaning that we might have acquired a sample from the tumor however not a part with PD-L1 expression or ≥50 PD-L1 expression which is the cut off measurement for first line single agent immunotherapy." (PMID 31598145, 2019). "An important mechanism explaining the melatonin-mediated inhibition of tumor growth is related to the inhibition of the phosphoinositide 3-kinase/protein kinase B (PI3K/AKT) and EGFR signaling pathways in various cancer cell lines." (PMID 31319607, 2019). "The inhibition of the epidermal growth factor receptor (EGFR) and vascular endothelial growth factor receptor (VEGFR-2) plays a crucial role in tumor suppression, angiogenesis, and metastasis." (PMID 32039146, 2019). "Our review indicates that the EGFR and YAP pathways regulate the tumor immune checkpoint PD-1/PD-L1 in EGFR-mutant NSCLC, and that EGFR-TKIs are appropriate therapy prior to ICIs when sensitive mutations appear." (PMID 31387256, 2019). "Angiogenesis is required for invasive tumor growth and metastasis, which is mediated through VEGF and EGFR." (PMID 31303863, 2019). "Taken together, our study revealed that miR-96 is a tumor inducer of NSCLC and forms ceRNA regulatory network with FOXO1 and DUSP1 genes to co-regulate NSCLC development depending on EGFR signaling pathway." (PMID 31579447, 2019).
tumor (continued). "There was not only a decrease in the expression of many growth factors including VEGF, PDGF, FGF, EGFR, and HGRF, all key to the proliferation of tumor cells, but also for stromal cells serving protumorigenic purposes." (PMID 31192543, 2019). "Overall, our results indicate a tumor-suppressive role of miR-1296-5p through the translational repression of oncogenic CDK6 and EGFR in GC." (PMID 30530570, 2019). "Mechanistically, western blot analysis of tumor tissues revealed that 15c attenuated H1975 xenograft tumor growth in vivo by suppressing the phosphorylation of FGFR1 and EGFR." (PMID 31998131, 2019). "Firstly, EGFR-TKI can inhibit the proliferation of tumor cells, inhibit the apoptosis pathway, and suppress DNA repair capability, making tumor cells more sensitive to RT." (PMID 31399067, 2019). "In tumours derived from MDA‐MB‐436–SGLT1 shRNA cells, SGLT1‐negative tumour regions showed reduced levels of EGFR phosphorylation." (PMID 31199048, 2019). "In contrast to the EGFR finding, for EpCAM retargeting a dependency on the RGD motif was observed in 2D tumor cell models." (PMID 31811202, 2019). "All tumors were analyzed using an NGS multi-gene panel that expands the tumor genetic portrait, including genes such as BRAF, ERBB2, KRAS, and MET in addition to EGFR and ALK/ROS1, in accordance with recently updated recommendations." (PMID 30669267, 2019). "miR-34a and miR-34a-5p function as tumor-suppressive miRNAs, inhibiting cell proliferation, cell-cycle progression, and cell invasion by targeting Notch1, Notch2, c-Met, CDK6, and EGFR." (PMID 30832246, 2019). "To broaden our research in novel anti-tumor lead compounds, we selected Cell Division Cycle 25B (CDC25B), a specific tyrosine phosphatase, and epidermal growth factor receptor (EGFR), an Erb family receptor, as screening targets." (PMID 31480659, 2019). "Lapatinib is another small molecule tyrosine kinase inhibitor of EGF that can effectively inhibit the ATP checkpoint and prevent homogenization and heterodimerization between EGFR and HER2, which can inhibit tumor cell growth." (PMID 31684985, 2019). "Significant reduction in the expression of VEGF, PDGF, FGF, EGFR, and HGRF, all key to the proliferation of tumor cells and stromal cells serving protumorigenic purposes was observed." (PMID 31192543, 2019). "As a consequence, high-affinity EGFR antibodies should exert less stimulatory and therefore less harmful effects on RAS mutant tumor clones than lower-affinity therapeutic antibodies that permit residual RTK-mediated signaling." (PMID 32039027, 2019). "The majority of studies focused only on verification if used EGFR inhibitors combined with MET inhibitors synergistically affect cell viability or tumor growth." (PMID 31649529, 2019). "Of these, 68 patients were resistant to EGFR-TKIs, 133 patients were EGFR-TKI treatment-naïve, and 106 patients were identified retrospectively to have matched tumor tissue EGFR genotyping results." (PMID 31413754, 2019). "In keeping with these findings in surgical tumour specimens, PPARα KD in GSC was found to significantly reduce the protein expression of EGFR in vitro." (PMID 30565681, 2019). "Anti‐CTLA4 antibody binds with the tumour cell‐intrinsic CTLA4 and activates the EGFR pathway to induce PD‐L1 expression." (PMID 30378264, 2019). "Studies have reported that the EGFR gene can affect GLUT-1 through a downstream pathway, thus further affecting tumor glucose metabolism." (PMID 31380265, 2019). "We revealed a novel angiogenesis-induced drug resistance mechanism and predicted a synergistic drug combination using an EGFR inhibitor and a VEGFR inhibitor targeting both tumor cells and angiogenesis, which was consistent with the experimental data." (PMID 31074391, 2019). "Gene amplification of EGFR is frequently seen in GBM, and a minority of tumor cells in GBM carries an exon deletion form, the EGFR variant III (EGFRvIII)." (PMID 31370819, 2019).
tumor (continued). "Our study further expounded the relationship between the EGFR drugs resistance and the integrin αvβ3 in NSCLC, which discloses a more fundamental role of integrin αvβ3 in tumor growth." (PMID 31316001, 2019). "The EGFR was found to be overexpressed in 90% of HNSCC patients and its high levels in the tumor tissue has been strongly correlated with worst clinical outcome." (PMID 31014274, 2019). "Genetic mouse models revealed that EGFR deletion attenuates mutant KRAS activity and transiently reduces tumor growth." (PMID 31612108, 2019). "For instance, the multikinase inhibitor sorafenib reduces tumor cell proliferation and angiogenesis in HCC, which is due in part to its interaction with receptors for several growth factors, such as EGF (EGFR), VEGF (VEGFR) and PDGF (PDGFR)." (PMID 35582588, 2019). "To investigate the role of Bnl signaling in EGFR-Pcn tumorigenesis, we overexpressed a dominant negative FGFR mutant in the tumor cells to block Bnl signaling (UAS-BtlDN)." (PMID 31568500, 2019). "Importantly, the prognostic significance of IL12B was further strengthened by its ability to stratify within many currently known prognosticators, including gender (female), age at diagnosis (>65 for OS), tumor stage I, with EGFR mutation, and without KRAS mutation." (PMID 31004093, 2019). "To confirm and validate these and other findings on the proteome level we performed immunohistochemical analyses for EGFR, MET, CA12 and AR on a number of tumours with low or high FPM values for the corresponding genes." (PMID 31747973, 2019). "We also designed analogous bsRICs labelled with 64Cu for PET of tumours that co-express HER2 and EGFR." (PMID 31659527, 2019). "Indeed, another type of Del mutation of EGFR, EGFR type III variant (EGFRvIII), which has a deletion in its extracellular domain, has been tested as a vaccine candidate, and triggered both potent antibody responses and T cell responses against tumor cells bearing EGFRvIII mutation." (PMID 31722672, 2019). "A phase III trial, KEYNOTE-024, compared pembrolizumab (PD-1 inhibitor) with platinum-doublet chemotherapy in EGFR/ALK-negative, advanced NSCLC patients with tumor positive for PD-L1 ≥ 50%." (PMID 31049758, 2019). "Western blotting was performed to verify the expression of phospho-EGFR and phospho-STAT3 in tumor tissues." (PMID 31422383, 2019). "The human epidermal growth factor receptor family consists of four members: EGFR (HER1, erbB1), HER2 (erbB2, neu), HER3 (erbB3) and HER4 (erbB4), all of which regulate the proliferation and differentiation of various tumour cells." (PMID 30858756, 2019). "To better understand and target SPINK1 driven tumor cell proliferation we need to further investigate the missing link between SPINK1 and EGFR signaling using modern methods and technologies." (PMID 30778387, 2019). "Using EGFR as a positive surface protein control, we found that 15–25% of both EGFR surface+ and PRL3 surface+ “live” tumor cells were viable (Annexin-V−), whereas the remaining population were in early stages of apoptosis (Annexin-V+)." (PMID 31171773, 2019). "In short, EGFR functions more as a driver oncogene in NSCLC, while EGFR plays a role as the component of one of the many pathways that contribute to tumor growth in CRC and HNC." (PMID 30700700, 2019). "Blocking mutant EGFR with TKIs can substantially inhibit MAPK/ERK and suppress tumor cell proliferation." (PMID 30935067, 2019). "The oncogenic effects of EGFR signaling in PDAC are likely to be directed by numerous effectors (including PI3-kinase and NFκB) that regulate tumor angiogenesis, as well as cell autonomous survival and proliferative processes." (PMID 31480737, 2019). "Another study showed that 65% of the primary CRC tumours, 66% of the metastases, and 43% of the matched primary CRC metastases were EGFR positive." (PMID 30858756, 2019).
tumor (continued). "In vivo studies showed that knockdown of hsa_circ_006100 delayed tumour growth, reduced PCNA expression and upregulated miR‐195 and BCL‐2 expression which was restored by miR‐195 inhibition due to GPRC5A/EGFR signalling, and changed the EMT phenotype in vivo." (PMID 31318114, 2019). "Meanwhile, increased expressions of EGFR and HER2 were reported to be involved in the enhanced tumor growth and chemoresistance induced by surgical stress from a laparotomy." (PMID 30216450, 2019). "Using adjacent tumour sections derived from MDA‐MB‐436–control shRNA cells, we observed positive SGLT1 and EGFR phosphorylation." (PMID 31199048, 2019). "EGFR, MAP kinase, TGFβ,60,105 and NF-kB,106,107 aid tumor development and progression as also participate in tissue repair, regeneration, and the healing processes in the postischemic recovery phase." (PMID 31637020, 2019). "This indicates that EGFR-NP and RGD-NP exhibited complimentary targeting of metastatic sites and their various tumor microenvironments." (PMID 31356633, 2019). "Conversely, blocking ERK signaling activity through expression of a dominant-negative form of EGFR and ERK and Ras RNAi constructs led to a reduction in scrib and dlg mutant tumor sizes at later stages." (PMID 31371383, 2019). "Erlotinib was an EGFR-tyrosine kinase inhibitor (EGFR-TKI) and the combined treatment of curcumin and erlotinib remarkably reduced tumor growth of erlotinib-resistant NSCLC cells in vivo." (PMID 31590362, 2019). "Wycoff and colleagues demonstrated how TAMs, usually located at the edge of the tumours, are stimulated by colony stimulating factor 1 (CSF1) to produce epidermal growth factor (EGF), the EGFR natural ligand." (PMID 31554160, 2019). "In MCF-7 cells, the treatment with the TKI vandetanib was effective on tumor growth; this response is eliminated by dual knockdown of RET and EGFR, thus establishing a link between expression of RET/EGFR and response to TKIs." (PMID 35582269, 2019). "In 1993, Rusch and colleagues demonstrated that the protein expression of EGFR is significantly increased in 45% of tumour lesions from NSCLC patients, while TGFα was overexpressed in 61% of those tumours." (PMID 31438559, 2019). "Our data clearly shows that tumor clones with EGFR ectodomain mutations are not sensitive to EGFR targeting, but don't seem to be stimulated by the antibody and therefore may have a lesser growth advantage than RAS mutant subclones during EGFR-directed therapeutic pressure." (PMID 32039027, 2019). "EGFR and PYGO2 mRNA expressions were assessed in tumor and corresponding normal margins in a sample of Iranian ESCC cases." (PMID 31470870, 2019). "In a separate experiment, EGFR and HER2 receptor status and downstream signalling intermediates were also analysed in primary tumours from control and neratinib-treated mice to corroborate our in vitro observations." (PMID 31409375, 2019). "Previous studies revealed that EGF activated EGFR and led to the activation of downstream signaling pathways, such as PI3K/AKT and MAPK/ERK, which are critical in metastasis and tumor progression." (PMID 31171012, 2019). "EGCG also shows a tumor suppression mechanism through inhibiting the phosphorylation of HER-2/neu and EGFR in ESCC cell line KYSE 150, resulting in the suppression of growth factor receptor." (PMID 30857144, 2019). "In summary, our results suggest that miR-141 functions as a tumor suppressor in HNSCC and that it suppresses tumor growth and metastasis by suppressing EGFR signaling." (PMID 30737360, 2019). "Based on our results, wild-type EGFR is important for proliferation and migration of KRAS-mutant tumor cells." (PMID 30935067, 2019). "IFIT1 and IFIT3 promoted EGFR activation in OSCC cells and enhanced the tumor-preventive activity of gefitinib." (PMID 31921891, 2019). "Both of these studies suggest utility of testing ctDNA BRAF levels in patients receiving combination therapy of anti-EGFR and BRAF inhibitor to monitor tumor response." (PMID 31824558, 2019).